CUL3 (cullin 3)
Diseases named in the same sentence as CUL3 in open-access papers (continued):
Sharing a sentence is not in itself a finding about the gene and the disease.
Hypertension (continued). "Of note, RhoBTB1 serves as a CRL3 substrate adaptor for the ubiquitination of PDE5, further suggesting that enhanced binding of variant CUL3 with substrate adaptors results in impaired substrate (i.e., RhoA and PDE5) ubiquitination and diminished vascular compliance in FHHt hypertension." (PMID 37845702, 2023). "We demonstrated that restoration of CUL3 expression could relieve hypertension through enhancing the effects of SHH activation on inhibition of apoptosis and oxidative stress as well as attenuating the proliferation and migration of VSMCs." (PMID 35715796, 2022). "Therefore, more in-depth research on CUL3 can deepen the understanding of the SHH pathway in hypertension." (PMID 35715796, 2022). "In the current study, our study aimed to prove that restoration of CUL3 gene expression relieved hypertension through enhancing the effects of SHH activation in inhibition of apoptosis and oxidative stress as well as attenuating the proliferation and migration of VSMCs." (PMID 35715796, 2022). "We aimed to investigate the role of Cullin3 (CUL3) in the regulation of hypertension." (PMID 35715796, 2022). "A reduction in CUL3 expression in VSM causes abnormal vasoconstriction and hence hypertension." (PMID 33928137, 2021). "The lack of CUL3 has been associated with defects in embryogenesis, hypertension, diminished angiogenesis, progressive interstitial inflammation, exacerbated colonic inflammation, and swelled spleens and lymph nodes." (PMID 34491895, 2021). "Vascular actions of CUL3 may contribute to hypertension, because McCormick and colleagues proposed that CUL3 regulates vascular tone via RhoA/Rho kinase signaling." (PMID 28804198, 2017). "Surprising is the severity of the hypertension, which may be explained in part on the basis of CUL3 actions in vascular cells." (PMID 26294796, 2015). "Variants in CUL3 are often associated with growth impairment in addition to hypertension and electrolyte imbalances and are commonly manifested in infants and children, while variants in KLHL3 and WNKs are associated with hypertension and electrolyte imbalances in mostly adult FHHt patients." (PMID 37845702, 2023). "Secondary hypertension can result from mutations of cullin-3 (CUL3); however, whether polymorphisms of CUL3 are associated with essential hypertension (EH) has not been reported." (PMID 28804198, 2017). "Due to the length of this paper, we only discussed the effects and regulatory mechanism of CUL3 and SHH signaling in hypertension in vitro and in vivo." (PMID 35715796, 2022). "Our findings suggested the importance of the balance between CUL3 and SHH signaling in the progression of hypertension, which provides a new understanding of the regulatory mechanism of this disease." (PMID 35715796, 2022). "Interestingly, although FHHt patients with mutations in CUL3, KLHL3 or WNK present the same clinical symptoms, those with mutations in CUL3 have a more severe phenotype, evident in terms of both an earlier age-of-onset and the degree of hypertension and electrolyte disturbance reported." (PMID 27815594, 2017). "However, the relation and balance between CUL3 and SHH signaling in hypertension draw our research interests." (PMID 35715796, 2022). "We demonstrated that restoration of CUL3 expression could protect against hypertension through enhancing the effects of SHH activation on inhibition of apoptosis and oxidative stress for hypertension and alleviating the dysfunction of VSMCs." (PMID 35715796, 2022). "Pseudohypoaldosteronism type II (PHAII) is a hereditary hypertensive disease caused by mutations in four different genes: with-no-lysine kinases (WNK) 1 and 4, Kelch-like family member 3 (KLHL3), and cullin 3 (Cul3)." (PMID 26490675, 2015). "Drugs that can target CUL3 and SHH might have the potential to hypertension therapy in the future." (PMID 35715796, 2022).
Hypertension (continued). "Therefore, increasing the expression of CUL3 while using SHH activators could not only play an anti-apoptotic and anti-oxidative role in the SHH pathway, but also reduce the level of excessive proliferation and migration of VSMCs, thereby hindering the development of hypertension." (PMID 35715796, 2022).
autism (23 papers, 2018 to 2025). Persistent deficits in social interaction and communication and interaction as well as a markedly restricted repertoire of activity and interest as well as repetitive patterns of behavior. "Mutations of the Cullin-3 (Cul3) E3 ubiquitin ligase are associated with autism and schizophrenia, neurological disorders characterized by sleep disturbances and altered synaptic function." (PMID 39841692, 2025). "Cul3 mutations are a risk factor for autism and schizophrenia, neurological disorders associated with disturbed sleep and changes in neuronal synapses." (PMID 39841692, 2025). "Cul3 mutations disrupt brain development and physiology and contribute to neurological disorders, including autism and schizophrenia." (PMID 39841692, 2025). "For genes such as Cul3 for which neuronal function remains underexplored, homozygous deletion is among the best tools to elucidate function, particularly for autism risk genes." (PMID 38803442, 2024). "We previously generated a forebrain-restricted Cul3 conditional knockout mouse using Emx1-Cre recombination; this mouse recapitulates core behavioral abnormalities associated with autism." (PMID 36693858, 2023). "The largest array of SPARK analysis findings to date (including 42,607 autism cases) identified CUL3 as a genetic high-confidence LoF variant." (PMID 37575562, 2023). "Naturally occurring de novo mutations that cause loss-of-function in the Cul3 ubiquitin E3 ligase gene were identified in exome sequencing studies of people with autism." (PMID 37428799, 2023). "Monoallelic Cul3 ablation in ChAT+ neurons recapitulated social preference deficits similar to those seen in mice with Cul3 deficiency in forebrain glutamatergic neurons and other Cul3 models of autism." (PMID 36693858, 2023). "Existing medical research suggests that CUL3 mutations are closely related to neurodevelopmental disorder with or without autism or seizures (neurodevelopmental disorder with autism and seizures, OMIM: 619239)." (PMID 37026922, 2023). "KCTD13 modulates synaptic transmission by suppressing RHOA signalling via interaction with the ubiquitin ligase CUL3, itself an autism risk factor." (PMID 36658491, 2023). "Large scale unbiased genetic screening identified recurrent de novo heterozygous loss of function mutations of Cullin 3 (Cul3) in cohorts of patients with autism." (PMID 35204682, 2022). "A case in point is the gene encoding Cullin 3 (Cul3), a component of the E3 ubiquitin ligase complex that is a high-risk allele for autism and schizophrenia." (PMID 35204682, 2022). "Here, we show that insomniac (inc), a conserved adaptor for the autism-associated Cul3 ubiquitin ligase, acts in a restricted period of neuronal development to impact sleep in adult Drosophila." (PMID 34908527, 2021). "Here, we show that Drosophila insomniac (inc) short sleep mutants, which lack an adaptor protein for the autism-associated Cullin-3 ubiquitin ligase, exhibited enhanced Pavlovian aversive olfactory learning and memory, unlike other sleep mutants with normal or reduced memory." (PMID 40111981, 2025). "Another important unresolved question is whether heterozygous loss-of-function Cul3 mutations alter sleep in rodent models, analogous to sleep disturbances reported for human Cul3 mutations associated with autism." (PMID 39841692, 2025). "Interestingly, KCTD13 is an adaptor protein for CUL3, a ubiquitin ligase that has been characterized as a high-risk autism gene through genome-wide association studies." (PMID 37428799, 2023). "Recently, a CUL3 novel mutation was found in patients with autism." (PMID 36726778, 2023). "CUL3 knockout mice showed autism-associated behavioral phenotypes." (PMID 34073122, 2021). "As Inc functions as an adaptor for Cullin-3 E3 ligase-mediated ubiquitination, and Cullin-3 mutations have been associated with autism spectrum disorder, our findings provide a potential mechanistic connection between neurodevelopmental hyperfunction and the etiology of autism." (PMID 40111981, 2025).
autism (continued). "Furthermore, these results indicate that dysregulation of conserved substrates of Inc-Cul3 complexes may contribute to altered sleep and synaptic function in autism and schizophrenia associated with Cul3 mutations." (PMID 39841692, 2025). "However, loss of Cul3 in these mice was limited to glutamatergic neurons in the forebrain, and the model did not recapitulate the intellectual disabilities observed in patients with autism." (PMID 36693858, 2023). "Additionally, one of Cul3′s “adapters” is coded by chromosome 16p11.2, a locus that is subject to microdeletions and microduplications (i.e., copy number variants), and associated with autism and schizophrenia." (PMID 35204682, 2022). "Given the conserved functions of Cul3–inc complexes and the associations of Cul3 lesions with autism, elucidating inc substrates and their contributions to neurogenesis and neuronal anatomy may provide insights into brain development, tumorigenesis, and sleep disorders." (PMID 34908527, 2021). "There are other genes involved in ubiquitination, and recent work indicates that these also create autism-like symptoms in an animal model, as with CUL3, or are directly involved in human autism." (PMID 40650268, 2025). "Based on these studies, the Simons Foundation Autism Research Initiative (SFARI) gives Cul3 a SFARI Gene Score of one20, signifying it as a high confidence autism risk gene." (PMID 38233464, 2024). "We evaluated the behavioral effects of Cul3 haploinsufficiency in cholinergic neurons on autism-like behaviors, cognition, and motor function." (PMID 36693858, 2023). "Here, we developed a new mouse that relies on ChAT+ cell-specific Cul3 deletion and studied the differential contribution of cholinergic neurons in the BF and STR to autism-associated behaviors and cognition." (PMID 36693858, 2023). "Specifically, Cul3 deficiency in the mPFC resulted in NMDAR hypofunction, a type of synaptic change frequently found in other genetic models of autism, such as Shank3 or Shank2 deficiency and 16p11.2 mice." (PMID 37575562, 2023). "Cul3+/− mice share similarities with other autism mouse models with regards to brain volumetric changes." (PMID 33727673, 2021). "Furthermore, we show that different molecular mechanisms converge on similar behavioural phenotypes by demonstrating that the autism models Cul3 and Ptchd1, despite having similar behavioural phenotypes, differ in their functional and molecular alteration." (PMID 38857283, 2024). "CUL3, coding for a Cullin family scaffold protein mediating assembly of ubiquitin ligase complexes through BTB domain substrate-recruiting adaptors, has been identified as a high-risk gene for autism." (PMID 37428799, 2023). "Although some ASD mouse models exhibit a reduced E/I ratio, such as mice with autism-associated mutations in NRXNs or SHANKs, an enhanced E/I ratio can also be observed in many other ASD mouse models, such as TSC1-, MDGA2-, FMRP-, or CUL3-deficient mice." (PMID 34848499, 2022). "Thus, reduced neurite outgrowth in Cul3+/− cortical neurons, possibly due to upregulated RhoA signaling, could be a shared phenotype among different autism models, including Cul3+/−." (PMID 33727673, 2021). "Therefore, Smyd3 may be a potential therapeutic target for Cul3-related autism." (PMID 37575562, 2023). "CUL3 neurodevelopmental disorder with or without autism or seizures, with autosomal dominant inheritance pattern, is characterized by global developmental delay evident in childhood, impaired intellectual development, and speech delay." (PMID 39941308, 2025).
lung cancer (19 papers, 2014 to 2025). A malignant neoplasm involving the lung. "Consistently, treatment of breast and lung cancer cells with a specific Cul-3 inhibitor (DI-1859) also caused SLC7A11 accumulation in a dose-dependent manner." (PMID 38959043, 2024). "CUL3 mutation or down-regulation is observed in different types of cancer including lung cancer, oral squamous cell carcinoma and other squamous cell cancers, sporadic PRCC2 (type 2 papillary renal cell carcinoma) and liver cancer." (PMID 32346533, 2020). "For example, somatic gain-of-function mutations of Nrf2 or somatic loss-of-function mutations of either Keap1 or Cullin 3 (Cul3) are frequently reported in lung cancer." (PMID 31811110, 2019). "KEAP1, NFE2L2, and CUL3 are responsible for dysregulation of oxidative stress pathway in lung cancer and they have been shown to have elevated mutation rates in NSCLC." (PMID 30992440, 2019). "By negatively regulating ACLY, CUL3 inhibits lipid synthesis, cell proliferation, and xenograft tumor growth in lung cancer cells." (PMID 39944823, 2025). "The treatment of lung cancer was gradually developing, but the patients with KEAP1/NFE2L2/CUL3 mutations were in a dilemma." (PMID 34617407, 2021). "The authors functionally validated the tumor suppressive role of CUL3 in A549 and H522 human lung cancer cell lines and showed that shRNA knockdown of this gene increased proliferation rates, relative to control." (PMID 33435458, 2021). "Collectively, these data suggest that CUL3 plays a critical role in decreasing SOX9 protein abundance, which is associated with HCC and lung carcinoma progression." (PMID 33173725, 2020). "NRF2 is frequently upregulated in lung cancer as a consequence of somatic mutations in KEAP1, NFE2L2, or CUL3, and associates with increased cell proliferation and resistance to anticancer drugs." (PMID 29102676, 2018). "Non‐small cell lung cancer (NSCLC), which accounts for ~ 80–85% of all lung cancer cases, exhibits mutations, or copy number alterations in NFE2L2/NRF2 or its degradation machinery (KEAP1, CUL3, or RBX1) in > 30% of NSCLC cell lines and patient tissues." (PMID 35184380, 2022). "In addition, a recent study using a transposon mutagenesis screen in mice indicates that CUL3 is a tumor suppressor in lung cancer." (PMID 32346533, 2020). "In a lung cancer study, samples were taken from 178 lung squamous cell carcinomas (SqCCs) and, apart from 53BP1, most mutations were found in three genes associated with the Nrf2–ARE pathway, NFE2L2 (the gene name of Nrf2), Keap1, and Cul3 (the gene name of Cullin 3)." (PMID 27047795, 2016). "The E3 ligase CUL3 interacts with its adaptor protein KLHL25 to degrade ACLY in cells, thereby inhibiting lipid synthesis and growth of lung cancer cells." (PMID 39944823, 2025). "A Kelch-like family member, KLHL25, bound cul3 to ubiquitinate and degrade ACLY, thereby inhibit inhibits tumor progression of lung cancer cells." (PMID 33109073, 2020). "CUL3 plays an important role in ubiquitination of KEAP1, a negative regulator of the transcription factor NRF2 which enacts a transcriptional program important in protecting lung cancer and other tumor types from oxidative stress." (PMID 33435458, 2021).
pseudohypoaldosteronism type 2 (17 papers, 2013 to 2025). A rare inherited form of hypertension characterized by hyperkalemia, hyperchloremic metabolic acidosis, normal or elevated aldosterone, low renin, and normal renal function. "Pseudohypoaldosteronism type II is also caused by mutations in the cullin-3 (CUL3) and kelch-like 3 (KLHL3) genes." (PMID 38691164, 2024). "Autosomal dominant mutations in CUL3 causes the most severe form of familial hyperkalemic hypertension." (PMID 35715796, 2022). "Autosomal dominant mutations in CUL3 cause the most severe form of familial hyperkalemic hypertension." (PMID 35715796, 2022). "The only known exception is the deletion of CUL3 exon 9 by a specific dominant splice site variant causing a severe form of pseudohypoaldosteronism type II (PHAII), featuring hypertension, hyperkalemia, and metabolic acidosis but not ASD15–17." (PMID 34031387, 2021). "Pseudohypoaldosteronism type 2 (PHA2), also known as Gordon syndrome, is a rare genetic disorder associated with variants in WNK1, WNK4, KLHL3, and CUL3." (PMID 39527282, 2025). "Pseudohypoaldosteronism type II (PHAII), also called Gordon syndrome, is a rare hereditary disease caused by variants in the WNK1, WNK4, KLHL3 and CUL3 genes." (PMID 34022862, 2021). "What highlights the role of CUL3 in cardiovascular disease is the identification of dominant-negative CUL3 mutations in patients with severe forms of familial hyperkalemic hypertension (FHHt)." (PMID 35327608, 2022).
autism spectrum disorder (15 papers, 2017 to 2025). A spectrum of developmental disorders that includes autism, and Asperger syndrome. "Proteomic analysis revealed that EIF4G1 was a potential target of Cullin 3 (CUL3) deficiency, a risk factor for autism spectrum disorder (ASD) and SCZ that caused cellular and behavioral defects." (PMID 40078531, 2025). "CUL3 is associated with a neurodevelopmental disorder (OMIM 619239) characterized by autism spectrum disorder, developmental delay, and cognitive developmental impairment with variable severity and age of onset." (PMID 40225944, 2024). "Mutations in Cullin-3 (Cul3), a conserved gene encoding a ubiquitin ligase, are strongly associated with autism spectrum disorder (ASD)." (PMID 38233464, 2024). "Recent studies have identified Cul3 as a high-confidence risk gene in neurodevelopmental disorders (NDDs), especially autism spectrum disorder (ASD)." (PMID 37575562, 2023). "Previous studies proved CUL3 is a high-confidence risk factor for autism spectrum disorder and developmental delay." (PMID 34073122, 2021). "E3-ubiquitin ligase Cullin3 (Cul3) is a high confidence risk gene for autism spectrum disorder (ASD) and developmental delay (DD)." (PMID 33727673, 2021). "De novo loss of function mutations in the ubiquitin ligase-encoding gene Cullin3 (CUL3) lead to autism spectrum disorder (ASD)." (PMID 34031387, 2021). "Cul3 lesions have been associated in several studies with autism spectrum disorders and comorbid sleep disturbances." (PMID 28558011, 2017). "Cul3 mutations have been associated with autism spectrum disorder (ASD)." (PMID 38233464, 2024). "However, the number of published case reports of autism spectrum disorder due to CUL3 gene mutations is limited." (PMID 37026922, 2023). "Exome sequencing studies have identified at least 20 mutations in the Cul3 gene (13 protein-truncating mutations and 7 missense) in the patients with autism spectrum disorder (ASD), developmental delay (DD), and schizophrenia (SCZ), with no Cul3 mutations detected in healthy controls." (PMID 33727673, 2021). "Loss-of-function mutations of the gene Cul3 have been identified as a risk factor for autism-spectrum disorder (ASD), but the pathogenic mechanisms are not well understood." (PMID 36693858, 2023). "The search terms employed were [(Cul3) OR (Cullin3)] and {[(NDD) OR (neurodevelopmental disorder)] OR [(ASD) OR (autism spectrum disorder)] OR [(DD) OR (developmental delay)] OR [(ID) OR (intellectual disability)] OR [(SCZ) OR (schizophrenia)]}." (PMID 37575562, 2023). "Also, CUL3 and PHIP are both genes known to be involved in autism spectrum disorders." (PMID 39501558, 2024).